HMGB1 (high mobility group box 1)
Diseases named in the same sentence as HMGB1 in open-access papers (continued):
Sharing a sentence is not in itself a finding about the gene and the disease.
tumor (continued). "Notably, cluster of differentiation 97 (CD97) and high mobility group box 1 (HMGB1) promote tumor cell metastasis and are crucially correlated with patient clinical stage and prognosis." (PMID 40066262, 2025). "HMGB1, released by dying tumor cells, may be recognized by DCs in a Toll-like receptor 4 (TLR4)- and myeloid differentiation primary response gene 88 (MyD88)-dependent manner, leading to a potent immune response." (PMID 39857785, 2025). "Necrotic tumor also releases pro-inflammatory molecules such as interleukin-33 or HMGB1, which may foster tumor growth." (PMID 40815430, 2025). "Tumor-associated neutrophils (TANs) display elevated PANoptosis gene expression and play pro-tumor activity with DCs via GATA-binding protein 2 (GATA2)-HMGB1-TIM-3 pathway, thereby hindering anti-tumor immunity and facilitating immune evasion of non-small cell lung cancer cells." (PMID 40721869, 2025). "Moreso, the expression of calreticulin (CRT) on the surface of tumor cell triggers the release of DAMPs, such as HMGB1 and ATP, signals which could further enable antigen-presenting cells (APCs) to phagocytes dying tumor cells and present tumor antigens." (PMID 41295214, 2025). "Similarly, in glioblastoma, TP73-AS1-mediated activation of the HMGB1/RAGE pathway enhances tumor cell proliferation and invasion, confirming its role as a critical oncogenic lncRNA." (PMID 40332793, 2025). "However, its therapeutic potential and molecular mechanisms in HMGB1-induced tumor angiogenesis remain unexplored." (PMID 40323970, 2025). "As previously reported, activation of either HMGB1 or NF‐κB crosstalk could lead to multiple drug resistance in tumours, especially chemotherapy." (PMID 39904827, 2025). "In addition, HMGB1 can exert anti-tumor effects by inducing apoptosis and inhibiting proliferation of tumor cells." (PMID 40969278, 2025). "Tumor cells undergoing ICD release or express ICD‐related damage‐associated molecular patterns (DAMPs), such as calreticulin (CRT), high mobility group box‐1 protein (HMGB1), adenosine triphosphate (ATP), and interferon‐β (IFN‐β)." (PMID 40504080, 2025). "Immunofluorescence staining for ICD revealed that tumor cells treated with SPNe under NIR irradiation exhibited an HMGB1 mean fluorescence intensity (MFI) of 20.4% compared to non-irradiated controls, confirming SPNe-mediated 1O2 generation for tumor cell killing and ICD induction." (PMID 40363042, 2025). "Key in vivo endpoints will include tumor growth inhibition and tumor rechallenge studies, animal survival, and spatial distribution of ICD markers (e.g., HSP‐70, calreticulin, HMGB1) and tumor‐infiltrating CD8+ T cells with respect to V‐LNP distribution and incident light propagation in tumors." (PMID 41256215, 2025). "In high-risk patients, cisplatin may enhance antigen presentation by dendritic cells via the release of immune-stimulatory molecules such as calreticulin (CRT) and HMGB1, thereby activating T-cell-mediated anti-tumor responses." (PMID 41170198, 2025). "In in vivo studies, inhibition of both HMGB1 and NETs delayed tumor growth." (PMID 41019086, 2025). "Furthermore, certain DAMPs, including HMGB1, S100 proteins, and IL-1α, not only accelerate tumor progression but also contribute to resistance against anticancer therapies." (PMID 40877572, 2025). "Furthermore, strong ICD induced release of damage‐associated molecular patterns (ATP, HMGB1, and CRT) from tumor cells, effectively activating the maturation of DC cells and CD8+ T cell infiltration." (PMID 40585770, 2025). "Furthermore, non-coding RNAs (e.g., LINC00665 and circ0000670) contribute significantly to tumor progression by interacting with critical molecules within the Wnt pathway (such as Wnt3a and HMGB1)." (PMID 40951343, 2025).
tumor (continued). "In the tumor microenvironment, HMGB1 modulates immune cell composition by depleting immunosuppressive cells (MDSCs, Tregs), increasing immunostimulatory cells (DCs, pDCs), and shifting macrophage polarization, thereby enhancing the anti‐tumor efficacy of the immune system." (PMID 41354099, 2025). "Preclinical research on mice supports this hypothesis: in a laboratory model, morphine combined with tumor-derived alarmins (like HMGB1) markedly increased NET release from neutrophils." (PMID 41516032, 2025). "Compared with RT alone, the tumors treated with therapeutic preparations containing radiosensitizer Hf and RT displayed the most severe DNA damage, accompanied by increased calreticulin (CRT) exposure and high mobility group box 1 (HMGB1) release, which effectively improved tumor immunogenicity." (PMID 40761180, 2025). "Interestingly, we observed a slight reduction in the tumor cell growth rate following HMGB1 knockdown, suggesting a protumor role of HMGB1, as reported in other studies." (PMID 40082916, 2025). "HMGB1 release from tumor spheres was almost 3 times higher compared to the adherent cells." (PMID 40647457, 2025). "Thus, just as it was shown for other TREM-1 ligands (Tag7, peptide N3, Hsp70, HMGB1), cytotoxic lymphocytes activated by the sum of peptides N9 and N15 induced apoptosis and necroptosis in tumor cells." (PMID 40362307, 2025). "HMGB1 modulates the formation, self‐renewal, and CSCs, thereby driving malignant tumor progression." (PMID 41354099, 2025). "In lung adenocarcinoma models, radiotherapy induces tumor cells to release HMGB1, which activates CAFs through the TLR4/PI3K/AKT pathway—driving conversion to the myCAFs phenotype with upregulated FAP, α‐SMA, and Collagen I expression, thereby enhancing tumor fibrosis and invasiveness." (PMID 41354099, 2025). "However, HMGB1 increase was evident locally at the tumor site after ECT, while it was undetectable in untreated tumors." (PMID 40007542, 2025). "Furthermore, in tumor cells, Cu was able to affect immune system regulation and increase the extracellular release of HMGB1." (PMID 41301513, 2025). "Our results suggest that serum HMGB1 concentration primarily reflects tumor burden, which is a potential confounder and therefore may not be a reliable biomarker of response to ECT." (PMID 40007542, 2025). "Tumor-microenvironment interactions further reinforce HMGB1-mediated apoptosis resistance." (PMID 41465435, 2025). "The PTA, upon light absorption, elevates the temperature, inflicting damage to and causing the demise of tumor cells while also facilitating the release of intracellular DAMPs such as CRT, HMGB1, and ATP into the extracellular environment through the process of ICD." (PMID 40040955, 2025). "In early‐stage tumorigenesis, HMGB1‐induced autophagy promotes the selective clearance of damaged organelles and misfolded proteins, thereby preserving intracellular homeostasis to enhance tumor cell survival and proliferative capacity." (PMID 41354099, 2025). "In HMGB1-deficient subcutaneous tumor model mice, both the therapeutic efficacy of ADVNE and ADVPPE and their ability to promote M1 macrophage polarization and TEM/TE infiltration in the tumor microenvironment were significantly reduced." (PMID 40082916, 2025). "This demonstrates the dual role of IGF2BP3 and HMGB1 in tumor development and treatment." (PMID 38504159, 2024). "Collectively, this study suggests that MSI2 may ﻿improve the prognosis of CRC patients by reprogramming the tumor immune microenvironment (TIME) through HMGB1-mediated PTMs, which ﻿might be a novel therapeutic option for CRC immunotherapy." (PMID 38347600, 2024). "In addition to stimulating antigen-presenting DCs, high mobility group box 1 protein (HMGB1) in tumor cells secretes adenosine triphosphate (ATP) to recruit DCs to tumors." (PMID 38868091, 2024).
tumor (continued). "Furthermore, apart from these biological processes related to tumorigenesis, HMGB1 is also involved in tumor invasion and metastasis, which are the foremost distinguishing features of malignant neoplasms." (PMID 38504159, 2024). "Research has identified a tumor-promoting cluster of TANs characterized by increased expression of HMGB1 that may interact with the TME through HMGB1-TIM-3 axis." (PMID 38877579, 2024). "Furthermore, pharmacologic inhibition of TLR4 with a cell permeable inhibitor or depletion of HMGB1 using neutralizing antibodies or HMGB1-specific siRNA reduced the efficacy of anti-tumour vaccination." (PMID 38353760, 2024). "When the tumor is irradiated, the release of HMGB1 from damaged tumor cells may lead to NETs formation in a TLR4‐dependent manner." (PMID 39015554, 2024). "Besides its immune functions, HMGB1 exhibits tumor suppression and oncogenic functions in the context of receptors, targeted cells, and redox status." (PMID 39759512, 2024). "Additionally, future research is required to explore the exact molecular mechanisms of the HMGB1/RAGE axis in tumor cell apoptosis and search for more drugs having the potential to regulate HMGB1/RAGE axis." (PMID 38529373, 2024). "Extracellular HMGB1 interacts with RAGE to stimulate tumor growth." (PMID 38529373, 2024). "In addition, CRT and HMGB1 secretion were detected from excised tumor tissue, with the highest expression levels detected in the H@Gd-NCPs treated group following radiation." (PMID 39769944, 2024). "In neurological cancers, it has beenreported that NETs generate by tumor-infiltrating neutrophils (TINs) regulated the connection between glioma and tumor microenvironment in patients with malignant glioma via the mediation of HMGB1/RAGE/IL-8 axis." (PMID 38188146, 2024). "In the case of radiotherapy and other DNA damage treatments, the induction of immunogenic cell death will promote the release of tumor antigens and DAMPs such as high mobility group box 1 (HMGB1) and adenosine triphosphate (ATP), triggering the innate immune reaction." (PMID 38256021, 2024). "Such inhibitors, if designed to specifically target the intracellular or extracellular functions of HMGB1, could potentially enhance tumor therapy by blocking autophagy and nuclear homeostasis." (PMID 38725632, 2024). "The study suggests that ZEB2-AS1 may act as an oncogene by mediating the miR-204/HMGB1 axis and promoting tumor cell growth and migration by affecting the epithelial-mesenchymal transition (EMT) process in PDAC." (PMID 38672671, 2024). "However, the regulation of HMGB1 by RBPs is still largely uncharacterized, as is tumor immunometabolism." (PMID 38347600, 2024). "In addition, personalized therapy for tumors is also a research hotspot, and further research can explore the different responses of patients to anti-tumor drugs, as well as the role of the HMGB1/RAGE axis in this process." (PMID 38529373, 2024). "Furthermore, the distinct roles played by the reduced and oxidized states of HMGB1 in tumor cells necessitate further exploration." (PMID 38529373, 2024). "Similarly, HMGB1 released after iron death of tumor cells induces polarization of M2-type macrophages by binding to AGE." (PMID 38816871, 2024). "Hence, HMGB1 holds promise as a biomarker to monitor tumor response during the chemoradiotherapy of HNSCC." (PMID 37897664, 2024). "Cytoplasmic HMGB1 expression was associated with poor tumour grade, but no other clinicopathologic characteristics in the CRC group." (PMID 38353760, 2024). "Additionally, the role and mechanism of the HMGB1/RAGE axis in promoting tumor proliferation in other tumor types such as osteosarcoma, lung cancer, and thyroid cancer remain to be elucidated." (PMID 38529373, 2024). "High mobility group protein 1 (HMGB1) plays a complex role in tumor biology." (PMID 38529373, 2024).
tumor (continued). "Our study shows that, in addition to its function on immune cells, the CXCL12/HMGB1 heterocomplex fine tune modulates CXCL12 activity on tumor cells, and suggests disruption of the complex as a novel therapeutic strategy for inhibiting cancer cell migration and invasion." (PMID 38803493, 2024). "HMGB1 can regulate the tumor micro-environment of OSCC by mediating the NF-κB signaling pathway." (PMID 37897664, 2024). "Tumor-induced HMGB1 has also been identified as a stimulator of cancer-associated NETosis." (PMID 38474175, 2024). "Finally, a multivariate analysis should have been carried out to jointly evaluate the prognostic impact of HMGB1 concentrations, PD-L1 expression, and other outcome-related factors such as tumor size and TNM stage." (PMID 39572927, 2024). "On the other hand, some of them can induce immunogenic cell death (ICD), inducing exposing calreticulin (CRT), releasing damage-related molecular pattern (DAMP) tumor antigens such as high-mobility group box 1 protein (HMGB1), and enhancing tumor immunogenicity." (PMID 38594751, 2024). "The study also confirmed in vivo that exosomal HMGB1 inhibits the growth of GC, suggesting a complex role where HMGB1 might modulate tumor microenvironment dynamics to influence cancer progression." (PMID 38816455, 2024). "Some of the DAMPS associated with tumor immunity are calreticulin, extracellular ATP, and high-mobility group box 1 protein (HMGB1), which favor DC maturation and priming of protective T-cell responses that can kill tumor cells and establish anti-tumor immunological memory." (PMID 39456655, 2024). "Feng and Chen reported that silencing of HMGB1 combined with docetaxel could inhibit the proliferation of prostate cancer cells, promote cell apoptosis, and hinder tumor formation." (PMID 37897664, 2024). "Finally, the inhibition of GPR65 or the blockage of HMGB1 effectively alleviated the tumor-promoting effects of lactate-stimulated TAMs." (PMID 38576043, 2024). "This article focuses on the role and mechanism of HMGB1 and its receptors in tumor development." (PMID 38529373, 2024). "Also during ICD, the release of HMGB1, IFNβ, and ATP from tumor cells further stimulates the maturation of DCs11,27." (PMID 38755254, 2024). "The HMGB1/RAGE axis is an important target for treating tumor angiogenesis." (PMID 38529373, 2024). "Tumor patients showing Cyto-HMGB1 translocation and PD-1+tumor-infiltrating lymphocytes (TILs) pre-treatment exhibit better clinical outcomes, possibly due to HMGB1 release inducing DC maturation via TLR4 activation." (PMID 38930793, 2024). "We therefore hypothesized that IGF2BP3 could elevate HMGB1 expression and promote tumor progression." (PMID 38504159, 2024). "In addition, the ICD effect induced by the different treatments was investigated using immunostaining of tumor sections for HMGB1, CRT, and HSP70, and the corresponding fluorescence intensities were determined." (PMID 38742454, 2024). "Another consideration is the dual role of HMGB1 in tumor immunity, which varies with its redox state: reduced HMGB1 stimulates the immune system, whereas oxidized HMGB1 may suppress it." (PMID 38844964, 2024). "Similarly, cisplatin induces HMGB1 expression in tumour cells, which in turn suppresses cisplatin‐induced apoptosis." (PMID 38783482, 2024). "Compared to KD-Control-A375, HMGB1-KD-A375 significantly decreased tumor cell migration." (PMID 39039072, 2024). "It has been reported that high mobility group box 1 (HMGB1) could both promote tumor cell proliferation and enhance T cell–dependent antitumor immunity." (PMID 37883181, 2024). "The TDCA-CM greatly facilitated tumor cell viability, invasion, and motility in contrast to the co-culture with the control, while HMGB1 neutralizing Abs antagonized this effect." (PMID 38469295, 2024). "Considering the critical role of HMGB1/RAGE axis in tumor biology, HMGB1/RAGE may serve as a promising therapeutic target for cancers." (PMID 38529373, 2024).
tumor (continued). "On the one hand, HMGB1, as a damage-associated molecular pattern molecule (DAMP), can induce the maturation of dendritic cells (DCs), thereby promoting the generation and activation of CD8+T cells and promoting anti-tumor immune response." (PMID 39314628, 2024). "Numerous tumor types, including hepatocellular carcinoma, breast carcinoma, prostate cancer, colorectal cancer, and pancreatic cancer, have also been shown to overexpress HMGB1." (PMID 39583399, 2024). "In fact, the release of the main effectors of pyroptosis (IL‐1β, IL‐18 and HMGB1) breaks down the ‘cold’ tumour properties and increases the infiltration of anti‐tumour immune cells in the TME, while at the same time decreasing the infiltration of suppressor immune cells." (PMID 38652105, 2024). "Similarly, the overexpression of cytoplasmic Hmgb1 stimulates tumor cell proliferation and metastasis." (PMID 39165691, 2024). "Moreover, it contributes to tumor cell proliferation, invasion, and metastasis, and increased expression of HMGB1 has been correlated with poor prognosis in various cancers." (PMID 38803493, 2024). "To investigate whether HMGB1 released from CRC tumor cells is responsible for MSI2-mediated immune activation in vitro and in vivo, we first treated stable SW620 and LOVO cells with Gly or DMSO for 24 h." (PMID 38347600, 2024). "The epithelial-to-mesenchymal transition (EMT) is a process driven by HMGB1, which may be an important factor responsible for tumor metastasis." (PMID 38725632, 2024). "To determine whether radiation-induced cancer cell death can elicit an anti-tumour immune response, we examined the release of HMGB1." (PMID 39372406, 2024). "These investigations suggest that the activation of the HMGB1/RAGE axis can stimulate autophagy in tumor cells by elevating the expression of autophagy-related proteins LC3 and Beclin-1, achieved through the activation of signaling pathways like PI3K/Akt, MAPK, and NF-κB." (PMID 38529373, 2024). "Notably, in the MCP‐inhibited cells, HMGB1 was released in large quantities at the onset of ferroptosis, which was crucial for inducing tumor‐suppressing pro‐inflammatory M1‐like macrophage polarization in our study." (PMID 38593415, 2024). "Furthermore, at 42 days post-injection, the tumor volume was notably reduced in mice treated with the HMGB1 inhibitor glycyrrhizin (group IV, U87 + shNC + glycyrrhizin) compared to the untreated group (group II, U87 + shNC)." (PMID 38576043, 2024). "Furthermore, enhancing USP50 expression in macrophages accelerated the promoting effect of TDCA-CM on the aggressive behavior of tumor cells, which was abolished by HMGB1 neutralizing Abs." (PMID 38469295, 2024). "In addition to inducing lethal DNA damage resulting in cell death, RT can induce immunogenic cell death (ICD) of tumor cells, which is characterized by the extracellular release of adenosine triphosphate (ATP) and high-mobility group box 1 protein (HMGB1)." (PMID 39355211, 2024). "Therefore, it came to the conclusion that IGF2BP3 activated the HMGB1 related pathways and participated in tumor progression of BLCA." (PMID 38504159, 2024). "In conclusion, our results presented here indicate that the regrowth of tiny populations of tumor cells may be triggered by a complex of two DAMPs, Hsp70 and HMGB1, marking a wide variety of relapsing tumors." (PMID 37880798, 2023). "IREB2, as an iron sensor, participates in the regulation of iron transport proteins and promotes iron uptake and ferroptosis in cancer cells, which significantly increases the release of HMGB1 in the tumor stroma and promotes the CD8+ T cells infiltration in cancer." (PMID 38288118, 2023). "In addition, HMGB1 as an essential regulator of autophagy is also involved in chemo resistance of tumor cells." (PMID 37098542, 2023). "Indeed, nuclear HMGB1 is involved in DNA repair, autophagy, and tumor radioresistance, while extracellular HMGB1 can stimulate tumor cell proliferation through the RAGE–Erk/p38 pathway." (PMID 36831435, 2023).